INS (insulin)
Diseases named in the same sentence as INS in open-access papers (continued):
Sharing a sentence is not in itself a finding about the gene and the disease.
diabetes (continued). "The fact that insulin is also a hormone convinces some experts that there is a relationship between insulin and vitamin D, and it also seems that many people with low vitamin D levels also develop general immunodeficiency, which can increase their incidence of diabetes and other diseases." (PMID 39290798, 2024). "In diabetes, pancreatic β-cells are locked in a vicious cycle, in which an impaired insulin response to glucose produces hyperglycemia, which makes β-cells more inefficient at insulin secretion, and an improvement in hyperglycemia results in at least a partial recovery of β-cell function." (PMID 38673770, 2024). "In addition, 1 case with diabetes mellitus required permanent insulin administration." (PMID 38780659, 2024). "A recent study conducted on a relatively small cohort (43 enrolled patients) indicated that nebivolol may improve insulin sensitivity and glucose utilization, potentially leading to better glycemic control in patients with diabetes mellitus or cardiometabolic syndrome." (PMID 39759452, 2024). "However, the effects of a diabetes diagnosis, as well as glucose homeostasis and insulin resistance/sensitivity, on the characteristics of a large number of retinal bands at distinct retinal locations over a large macular area have not, to date, been investigated." (PMID 38431705, 2024). "The Atherosclerosis Risk in Communities (ARIC) Study, which involved participants without cardiovascular disease or diabetes at the baseline, found fasting insulin to be positively associated with ischemic stroke risk after adjusting for age, sex, race, and study site." (PMID 39347227, 2024). "With the advancement of designer cell-based therapies, researchers are exploring ways to treat diabetes by modifying β cells because the current treatment for patients with type 1 diabetes is still limited to blood glucose monitoring throughout the day and insulin injections." (PMID 37847216, 2024). "However, some entire diabetic bitches under insulin treatment may experience diabetes poorly controlled during proestrus." (PMID 38539988, 2024). "Diabetes mellitus is a cluster of metabolic disorders characterized by elevated fasting and postprandial blood glucose levels, which may result from insufficient insulin production or insulin resistance." (PMID 38559692, 2024). "Finally, we sought to identify glucose-responsive promoters that might eventually be used to control the expression of an insulin gene in a bioengineered S. epidermidis strain developed to aid in treating diabetes." (PMID 39104585, 2024). "Patients with diabetes controlled with oral hypoglycemic agents (DM-oral) and those with insulin-controlled diabetes (DM-insulin) are both at a higher risk of AKI following cardiac surgery than the non-diabetic population (adjusted odds ratios: DM-oral = 1.26, DM-insulin = 3.92,)." (PMID 38562333, 2024). "Diabetes mellitus (DM) is a chronic metabolic disorder characterized by hyperglycemia resulting from defects in insulin secretion, insulin resistance, or a combination of both." (PMID 38464509, 2024). "Most people affected are with type 2 diabetes mellitus (T2DM), which is caused by a decline in the numbers or functioning of pancreatic endocrine islet cells, specifically the β-cells that release insulin in sufficient quantity to overcome any insulin resistance of the metabolic tissues." (PMID 38862980, 2024). "Diabetes mellitus (DM) is a chronic disease resulting from impaired secretion of insulin and/or impaired response to insulin." (PMID 38635535, 2024). "We hypothesized that greater difficulties regulating emotions would be significantly associated with worse self-management, adjusting for important patient characteristics related to self-care behaviors (i.e., insulin use, age, diabetes duration, insurance status)." (PMID 38671288, 2024).
diabetes (continued). "Regarding the mechanism for the association between diabetes and AD, a small but relevant study showed that those with MCI who progressed to dementia had a reduced cerebral metabolic rate of glucose metabolism, which is because cerebral insulin resistance is heightened in diabetics." (PMID 38542495, 2024). "Diabetes mellitus (DM) is a condition characterized by peripheral insulin resistance, hyperglycemia, and defective insulin secretion." (PMID 38666927, 2024). "Diabetes mellitus (DM), characterized by insulin resistance and β-cell dysfunction, manifests as a consequence of disrupted blood glucose homeostasis." (PMID 39272460, 2024). "The use of peripheral insulin administration for diabetes treatment can potentially cause hypoglycemia in non-diabetic individuals and may be ineffective due to impaired insulin transport across BBB." (PMID 38534454, 2024). "Diabetes mellitus (DM) is a persistent metabolic disorder characterized by continuous hyperglycemia resulting from impaired insulin secretion in the body." (PMID 38914599, 2024). "Finally, eight factors, including the abdominal circumference, duration of diabetes, blood glucose monitoring, oral hypoglycemic agents’ usage, cognitive impairment, hypertension, and insulin usage were included as predictive factors for hypoglycemia in elderly inpatients with T2DM." (PMID 39610841, 2024). "Diabetes mellitus (DM) is a chronic metabolic disorder characterized by elevated blood glucose levels due to impaired insulin production or utilization." (PMID 38731110, 2024). "Muscular dystrophy in diabetes could be due to reduced action of insulin action." (PMID 39125053, 2024). "Diabetes mellitus (DM) is characterized by hyperglycemia due to insufficient insulin production or utilization." (PMID 39642126, 2024). "Thus, liver-targeted insulin therapy could help restore normal postprandial liver glucose uptake and storage in individuals with diabetes." (PMID 39386695, 2024). "The mechanisms by which Chlorella may protect humans from diabetes and related risk factors are mainly unclear, the common explanation given is that the protective effect against diabetes by inducing insulin secretion, but also by increasing the circulating glucose uptake in the liver and muscles." (PMID 38625565, 2024). "Diabetes mellitus (DM) is a metabolic disease characterised by long-lasting hyperglycaemia resulting from defects from insulin secretion, insulin action, or both." (PMID 39271468, 2024). "The World Health Organization (WHO) defines diabetes as a complex metabolic disorder characterized by chronic hyperglycemia accompanied by disturbances in the metabolism of carbohydrates, lipids, and proteins due to defects in the secretion and/or action of insulin." (PMID 38738016, 2024). "Diabetes mellitus (DM) is a chronic metabolic disorder marked by hyperglycemia due to defects in insulin secretion, action, or both, with a global prevalence that has tripled in recent decades." (PMID 38927510, 2024). "Diabetes mellitus (DM) represents a significant global public health issue, characterized by chronic hyperglycemia resulting from issues in insulin secretion, insulin action, or both." (PMID 39188797, 2024). "Importantly, our biomics data, particularly the metabolomics, showed an enrichment of various diabetes-related pathways, including type I/II diabetes mellitus, IR, insulin secretion, diabetic cardiomyopathy, and AGE-RAGE signaling pathway in diabetic complications." (PMID 39840062, 2024). "Skeletal muscle may indirectly protect vascular structures of the erectile tissue through its role as a regulator of glucose and insulin homeostasis and prevent the progression of conditions characterized by dysregulated glucose and nutrients, like diabetes and metabolic syndrome." (PMID 38256560, 2024).
diabetes (continued). "Furthermore, the glucose metabolizing system of post-parturition cattle promoted the mechanism of insulin-independent glucose uptake that favors the mammary gland to prioritize milk production, which results in an insulin resistance status similar to human diabetes." (PMID 39339244, 2024). "There are two different types of DM; namely type I diabetes, characterised by an autoimmune disorder where pancreatic β-cells producing insulin are being attacked and destroyed by autoreactive immune cells." (PMID 38770527, 2024). "However, even though farm animals can experience high blood sugar, metabolic syndromes, and insulin resistance similar to clinical diabetes, there has been limited research focused on the mechanism of the modulation of insulin-dependent glucose metabolism in these animals." (PMID 39339244, 2024). "The implementation of a smartphone-based weekly communication and feedback platform between the interdisciplinary diabetes-in-pregnancy clinic team and patients with gestational diabetes mellitus enhanced glycemic control and patient compliance while reducing the need for insulin administration." (PMID 39651021, 2024). "Diabetes mellitus, commonly referred to as diabetes, is a group of metabolic disorders characterized by chronic elevation in blood glucose levels, resulting from inadequate insulin production, defective cellular response to extracellular insulin, and/or impaired glucose metabolism." (PMID 38444587, 2024). "However, the significant increase in insulin levels in both silibinin‐treated groups compared to the diabetes group implies that silibinin might enhance beta cell survival and avoid apoptosis, as shown in different studies." (PMID 38726421, 2024). "Furthermore, porcine insulin agents were previously used in clinical practice before the development of recombinant human insulin, indicating porcine insulin can be used to treat patients with diabetes." (PMID 38773268, 2024). "Thus, in this study we aimed to compare the effects of diabetes counselling: based on this newly developed module (USM-IAM) with that of standard counselling (SC) on insulin adherence, FBS and HbA1c among patients with uncontrolled T2DM in a 6 months’ duration study." (PMID 39020348, 2024). "However, when insulin-mediated metabolism is damaged due to diabetes, PI3K/Akt activation may be inhibited, resulting in neuronal damage." (PMID 38881175, 2024). "Consequently, therapies aimed at preventing oxidative stress, abnormal glucose homeostasis, insulin resistance, and the dysregulation of closely related processes, such as apoptosis, may represent an interesting approach against diabetes." (PMID 39339687, 2024). "Diabetes mellitus (DM) is a chronic, non-transmissible disease recognized as a leading cause of mortality globally, with high morbidity due to the chronic deterioration of insulin-producing cells." (PMID 39273600, 2024). "The lack of preserved C-peptide was associated with longer diabetes duration, glutamic acid decarboxylase autoantibody, and higher daily insulin doses, after adjustment {OR, 1.10 [interquartile range (IQR), 1.06–1.14]; OR, 0.46 (IQR, 0.27–0.77); OR, 1.04 (IQR, 1.02–1.06)}." (PMID 38405156, 2024). "Disruption of this equilibrium may lead to metabolic disturbances, insulin and leptin resistance coexist in diabetes, obesity and CVD due to both of them share the same signal transduction pathways such as protein tyrosine phosphatase 1B (PTP1B) and suppressor of cytokine signaling 3 (SOC3)." (PMID 39538244, 2024). "Furthermore, nutrition education provided through primary care providers or dieticians may potentially help patients taking insulin to improve dietary quality and support diabetes management." (PMID 39458437, 2024). "This risk is especially significant in non-smoking women, suggesting that insulin treatment for diabetes may independently increase the risk of lung cancer." (PMID 39044884, 2024).
diabetes (continued). "In addition, providers should make their patients aware early on of the fact that diabetes is a lifelong condition that may progress over time and thus requires medications on a chronic basis, including insulin, at some point in time." (PMID 39554530, 2024). "Insulin treatment improves glutamate uptake and prevents the diabetes‐induced increase in sodium‐independent glutamate uptake in glial cells, suggesting that insulin may improve the antioxidant status of the brain in diabetes." (PMID 38639646, 2024). "Thus, the interaction between CXCR1/2 and TNF-α signaling pathways may contribute to the dysregulation of insulin sensitivity and the pathogenesis of diabetes." (PMID 39627194, 2024). "This clearer definition in diabetes research could be due to self-care historically forming an important part of the transition of disease management tasks (such as glucose monitoring and insulin administration) from parents or carers to adolescents." (PMID 36641785, 2024). "In addition, the increased duration of diabetes may lead to financial challenges for families, as parents may struggle to afford the cost of medications (such as insulin) and ongoing care." (PMID 39895840, 2024). "Type 2 diabetes, also known as diabetes mellitus (DM), is a chronic metabolic disorder characterized by the body's reduced ability to utilize the hormone insulin efficiently and/or inadequate insulin production." (PMID 40496432, 2024). "Diabetes mellitus (DM) is a group of heterogeneous disorders of multiple etiologies characterized by chronic hyperglycemia resulting from defects in insulin secretion and/or insulin action." (PMID 39712180, 2024). "Additionally, four of the ten monogenic diabetes genes (HNF1A, GCK, ABCC8 and INS) exhibited P < 0.05 rare variant associations with youth-onset T2D in our primary gene-level analysis (which included both pathogenic and likely pathogenic and additional variants)." (PMID 38278947, 2024). "Diabetes is a clinically heterogeneous glucose intolerance syndrome, which is mainly due to the selectivity of immune mediated islet beta cell damage caused by a lack of insulin and glucose metabolism disorders." (PMID 38956257, 2024). "Furthermore, it is noteworthy that using IMA may increase the incidence of sternal wound complications in diabetes patients, especially those under insulin treatment." (PMID 38632609, 2024). "Previous research has also demonstrated that among a cohort of youth at risk for diabetes, there is an independent and positive relationship between total body fat mass and insulin secretion; conversely, there is a negative association with insulin sensitivity." (PMID 38191505, 2024). "The nurses, diabetes educators, and health counselors, along with the doctors and specialists, must counsel and educate the patients regarding the prescribed guidelines by the global and regional organisations for proper administration, storage, and usage of insulin injections." (PMID 38304656, 2024). "Diabetes mellitus (DM) is a complex metabolic and endocrine disorder characterized by abnormal insulin activity, reduced insulin sensitivity, and hyperglycemia." (PMID 38396842, 2024). "Thus, a cure for diabetes should entail replacement of insulin-producing β-cells." (PMID 38702347, 2024). "Diabetes mellitus (DM) is a chronic and systemic metabolic disease characterized by high blood glucose levels resulting from insufficient insulin secretion or insulin resistance." (PMID 39544236, 2024). "Insulin resistance (IR), defined as a reduced physiological response to insulin in target tissues, is recognized as a pathogenic induction factor for various metabolic syndromes, including nonalcoholic fatty liver disease (NAFLD), atherosclerosis, and type 2 diabetes mellitus (T2DM)." (PMID 39456499, 2024). "Moreover, patients who are prescribed insulin may have worse diabetes control or a more advanced DR." (PMID 38298309, 2024).
diabetes (continued). "We speculate that the patients under insulin yield a long-lasting relationship with their general practitioner, who was more likely to start an antimicrobial therapy than patients with newer onsets of diabetes mellitus." (PMID 39766526, 2024). "However, there have been case reports of pancreatitis or development or worsening of diabetes following COVID-19 infection and vaccination with BNT162b2 or mRNA-1273, both of which could affect plasma insulin levels." (PMID 39931577, 2024). "The advancement of light-activated insulin could revolutionize diabetes management." (PMID 38542928, 2024). "According to the American Diabetes Association, T1DM is defined as autoimmune β-cells destruction and death, typically resulting in absolute insulin deficiency, and T2DM is distinguished by a persistent reduction of β-cells mass loss and a progressive loss of insulin secretion." (PMID 38632264, 2024). "The principal cause of diabetes is insulin resistance, which occurs when bodily tissues (insulin-sensitive tissues such as the liver, adipose tissue, and muscles) do not respond appropriately to insulin, causing blood glucose to rise." (PMID 38539672, 2024). "However, insulin treatment per se in women with diabetes does not seem to be related to breast cancer risk." (PMID 39497166, 2024). "Diabetes mellitus (DM) is a chronic metabolic disorder characterized by hyperglycemia resulting from defects in insulin secretion, insulin action, or both." (PMID 38659550, 2024). "The most common endocrine and metabolic condition is diabetes mellitus (DM), which is brought on by either an absolute or insufficient release of insulin." (PMID 39596859, 2024). "Diabetes mellitus (DM) is a long-term metabolic disease characterized by high blood glucose levels followed by reduced insulin production in peripheral tissues." (PMID 38745820, 2024). "Also, in diabetics, it was stated thathyperglycemia, insulin resistance and free fatty acid release could lead to asignificantly increased oxidative stress, and therefore atherosclerosisacceleration." (PMID 39076504, 2024). "Therefore, we would like to increase the clinicians’ awareness of the risk of missing an opportunity to give effective CV-preventive drugs also to diabetes patients with longer duration, higher HbA1c, women and diabetes patients already on multiple diabetes treatments and insulin." (PMID 39113013, 2024). "Serial insulin dose adjustments can be suggested following monitoring guidelines, considering the control of the clinical signs, preferably using standardized scoring systems such as the Diabetes Clinical Score and glycemic variability evaluated in the blood, interstitium, and/or urine." (PMID 38539988, 2024). "Diabetes mellitus (DM) is a metabolic disease characterized by hyperglycemia, resulting from defects in insulin secretion or action." (PMID 38907737, 2024). "This traditional approach is thought to trigger a stress response due to prolonged fasting, which may disrupt insulin pathways by altering neuroendocrine and inflammatory responses, leading to perioperative insulin resistance, stress hyperglycemia, or perioperative diabetes." (PMID 39165509, 2024). "However, a cross-sectional study conducted between 2009 and 2010, which included 1,314 Korean patients older than 18 years with newly diagnosed diabetes, revealed that 59.5% of the subjects exhibited IR, and 20.2% had moderate to severe defects in insulin secretion as assessed by C-peptide levels." (PMID 39436903, 2024). "Diabetes mellitus (DM) is a ubiquitous chronic metabolic disorder brought on by insufficient insulin secretion and/or decreased tissue response to insulin in one or more organs along the complex hormonal pathways." (PMID 39620004, 2024).